INPP5E (inositol polyphosphate-5-phosphatase E)
Diseases named in the same sentence as INPP5E in open-access papers (continued):
Sharing a sentence is not in itself a finding about the gene and the disease.
Joubert syndrome (continued). "Mutations in ciliary proteins such as CEP290, ARL13B or INPP5E in Joubert syndrome may lead to important neurological disturbances in cerebellar development and defective formation of adult neuronal stem cells regions." (PMID 23205631, 2013). "Furthermore, we reveal that some Joubert syndrome mutations perturb INPP5E ciliary targeting, and clarify how each CLS works: (i) CLS4 recruits PDE6D, RPGR and ARL13B, (ii) CLS2-CLS3 regulate association to TULP3, ARL13B, and CEP164, and (iii) CLS1 and CLS4 cooperate in ATG16L1 binding." (PMID 36063381, 2022). "INPP5E is associated with Joubert syndrome (JBTS) and mental retardation, truncal obesity, retinal dystrophy, and micropenis syndrome caused by missense mutations in its phosphatase domain." (PMID 33711342, 2021). "In a zebrafish model of INPP5E-related Joubert syndrome, renal ciliogenesis defects were accompanied by defects in apical cortical actin organization, potentially reflecting a commonality with the actin cortical-clearing defects described in this paper." (PMID 37665101, 2024). "Mutations in INPP5E have been identified as causative factors for Bardet–Biedl syndrome (BBS) and Joubert syndrome (JBTS), both characterized by craniofacial abnormalities and skeletal anomalies, and categorized as cilia‐related diseases." (PMID 38514901, 2024). "Mutations in OCRL cause Lowe syndrome and Dent disease, and INPP5E mutations occur in MORM and Joubert syndromes." (PMID 33119550, 2021). "The tethering and fusion of autophagosomes and lysosomes are mediated by two regulatory factors, EPG5 and INPP5E, which are known to be responsible for two human hereditary disorders, Vici syndrome and Joubert syndrome, respectively." (PMID 32528724, 2020). "Other monogenic disorders of phosphoinositide metabolism include Lowe’s syndrome and Joubert syndrome, which can be caused by mutations in the inositol polyphosphate 5-phosphatases OCRL and INPP5E, respectively." (PMID 31034465, 2019). "Altogether, these data show that INPP5E ciliary targeting is sometimes affected in Joubert syndrome, which could contribute to pathogenesis in these cases." (PMID 36063381, 2022).
MORM syndrome (16 papers, 2011 to 2025). "While biallelic pathogenic variants in INPP5E are typically associated with JBTS1or MORM syndrome, our case, compound heterozygous for two known pathogenic missense variants, underscores the existence of a milder, isolated retinal phenotype." (PMID 41465079, 2025). "This association is strengthened by pathogenic variants in INPP5E accounting for both JS and MORM syndrome (mental retardation, obesity, retinal dystrophy, and micropenis)." (PMID 40710848, 2025). "On the other hand, MORM syndrome is resulted from C-terminal deletions of INPP5E, which leads to loss of the CAAX motif and exclusion of INPP5E from the ciliary membrane without affecting the catalytic activity." (PMID 36547473, 2022). "Mutations in 5′-phosphatase inositol polyphosphate 5-phosphatase E (INPP5E) is associated with truncal obesity, retinal dystrophy, mild mental retardation and micropenis (MORM) syndrome." (PMID 33627135, 2021). "The CaaX motif reportedly has a role in MORM syndrome, wherein a mutation causes the premature truncation of the INPP5E protein, thereby causing the protein to lose its C-terminal CaaX domain." (PMID 31252577, 2019). "Mutations in the inositol polyphosphate-5-phosphatase E (INPP5E) gene lead to MORM syndrome." (PMID 36568981, 2022). "Previous studies revealed that INPP5E, the inositol polyphosphate-5-phosphatase that is mutated in the developmental disorders Joubert and MORM syndromes, is essential for the function of the primary cilium and maintenance of phosphoinositide balance in nondividing cells." (PMID 28031327, 2017). "INPP5E is also a ciliary protein and is involved in the ciliopathies Joubert syndrome (JS) and MORM syndrome (an autosomal recessive congenital disorder)." (PMID 31252577, 2019). "It is important to note that Pik3caH1047R embryos exhibit an earlier more severe phenotype compared to Inpp5e-null embryos and that PROS does not phenocopy Joubert or MORM syndrome with INPP5E mutations, even though both result in increased ciliary PIP3." (PMID 39168978, 2024). "In addition to the developmental disorder Joubet Syndrome, mutations in 5′-phosphatase inositol polyphosphate 5-phosphatase E (INPP5E) causes moderate mental retardation, truncal obesity, retinal dystrophy, and micropenis (MORM) syndrome." (PMID 31507376, 2019).
Retinal dystrophy (9 papers, 2017 to 2025). Retinal dystrophy is an abnormality of the retina associated with a hereditary process. "CEP290 is the most frequent JBTS causative gene, but variants in AHI1 and INPP5E are the most frequently associated to retinal dystrophies." (PMID 35551639, 2022). "Pathological variants responsible for JBTS associated with retinal dystrophies involve AHI1 in 4 families, followed by CEP290 and INPP5E in 2 families each, and NPHP1 in one family." (PMID 35551639, 2022).
retinal degeneration (8 papers, 2020 to 2025). Degeneration of the retina. "Pathogenic variants in INPP5E lead to retinal degeneration as part of MORM and Joubert syndromes, and as non-syndromic isolated retinal degeneration." (PMID 39871753, 2025). "Deletion of Inpp5e in the retina with Six3-Cre blocked the formation of discs from the ciliary membrane and caused rapid retinal degeneration." (PMID 39871753, 2025). "The variant c.1393G > A (p.V465I) in the INPP5E gene was previously detected in a patient with inherited retinal degenerations, and c.669_670delGC (p.A223Afs*66) is firstly found in JS." (PMID 37735380, 2023). "To investigate how loss of INPP5e causes retina degeneration, we generated mice with a retina-specific KO (Inpp5eF/F;Six3Cre, abbreviated as retInpp5e−/−)." (PMID 33711342, 2021). "Human individuals with INPP5E pathogenic variants develop retinal degeneration." (PMID 39871753, 2025). "Of the 19 known pathogenic variants present in a homozygous state only three (p.[(Ser249Phe); (Arg596Thr)], p.(Val465Ile), p.(Arg621Trp)) resulted in a non-syndromic retinal degeneration, which may imply a hypomorphic or photoreceptor-specific impact of these variants on INPP5E function." (PMID 34188062, 2021). "In humans, inositol polyphosphate-5-phosphatase E (INPP5E) mutations cause retinal degeneration as part of Joubert and MORM syndromes and can also cause non-syndromic blindness." (PMID 39871753, 2025). "Importantly, retina-specific knock-out of Inpp5e in mice leads to impaired photoreceptor axoneme extension and rapid retinal degeneration." (PMID 40037334, 2025). "In particular, patients presenting NPHP associated with retinal degeneration more often had causative variants in CEP290 and INPP5E, while those with NPHP but lacking retinal disease had molecular defects in CC2D2A, TMEM67, and NPHP1." (PMID 35238134, 2022).
polycystic kidneys (7 papers, 2017 to 2024). "Moreover, the renal-specific deletion of Inpp5e exons 2-6 in mice resulted in severe polycystic kidneys and renal failure, likely caused by the hyperactivation of PI3K/Akt and mTORC1 pathway." (PMID 36547473, 2022). "Although most INPP5E-associated JBTS patients mainly show neurologic symptoms with rare kidney or hepatic features, both Inpp5eD/D and Inpp5e-/- mice showed polycystic kidneys with a 100% penetrance." (PMID 36547473, 2022). "The disease-associated variant in INPP5E has not been previously linked to this type of polycystic kidney disease, which is best described as diffuse cystic dysplasia." (PMID 30235266, 2018). "Knockout of the Inpp5e gene (Inpp5e−/−) in mice resulted in embryonic and early postnatal death with a phenotype that recapitulates JBTS, containing NTDs, polycystic kidneys and polydactyly." (PMID 34093381, 2021).
Lowe syndrome (6 papers, 2013 to 2024). "Specifically, we selected synaptojanin 1⁄2 (SYNJ1/2), INPP5E, INPP5J, oculocerebrorenal syndrome of Lowe (OCRL), INPP5B, and INPP5K, of which INPP5E/B and OCRL have already been shown to alter ciliary lipid composition." (PMID 38110903, 2023).
medulloblastoma (6 papers, 2020 to 2025). A malignant, invasive embryonal neoplasm arising from the cerebellum. "INPP5E expression was downregulated in a subset of patients with SHH medulloblastomas and correlated with enhanced overall survival." (PMID 39781470, 2025). "Firstly using AKT inhibitors in our PI3K-activated models, we confirmed the AKT/GSK3β cilia disassembly pathway that we previously proposed in Inpp5e-null medulloblastoma cells." (PMID 39168978, 2024). "INPP5E is reported to promote Sonic Hedgehog medulloblastoma progression via a phosphoinositide signaling axis at cilia." (PMID 34996491, 2022). "INPP5E, encoding inositol polyphosphate-5-phosphatase, promotes sonic hedgehog (SHH) signaling in SHH medulloblastoma by negatively regulating a phosphoinositide 3-kinase (PI3K) signaling axis that maintains primary cilia on tumor cells." (PMID 34760709, 2021). "The number of ciliated Inpp5e-null Hedgehog-dependent medulloblastoma cells was rescued by pan-PI3K inhibition and wild-type (but not catalytically inactive) INPP5E." (PMID 32970140, 2020). "Inpp5e-null Hedgehog-activated murine medulloblastoma cells exhibit reduced cilia assembly in vivo and in vitro, with increased transition zone PIP3 levels in cells isolated from this model." (PMID 32970140, 2020). "Pan-PI3K inhibition also rescued the increased ciliary PIP3 levels in these Inpp5e KO cells, collectively suggesting cilia-specific PIP3 signalling to AKT and thereby GSK3β inhibition may be an important regulatory mechanism controlling cilia dynamics in medulloblastoma." (PMID 32970140, 2020).
cystic kidneys (4 papers, 2018 to 2025). "Meanwhile, downregulating inpp5e in zebrafish causes abnormalities in cilia formation and leads to cystic kidney development." (PMID 39781470, 2025). "INPP5E is a pathogenic gene associated with Joubert syndrome, a disorder that affects multiple organs and leads to cystic kidneys." (PMID 38086423, 2023). "However, the molecular mechanism underlying INPP5E dysfunction and its contribution to abnormal ciliogenesis and cystic kidneys remain unknown." (PMID 38086423, 2023). "The buildup of these molecules restricts the normal ciliary transduction of Hedgehog signaling and the bulges in the ciliary shaft and tip seen in the SEM and TEM of the renal cyst-lining epithelium of Inpp5e knockout mice may be changes relating to the buildup." (PMID 30235266, 2018).
Leber congenital amaurosis (4 papers, 2021 to 2025). Leber congenital amaurosis (LCA) is a retinal dystrophy defined by blindness and responses to electrophysiological stimulation (Ganzfeld electroretinogram (ERG)) below threshold, associated with severe visual impairment within the first year of life. "Herein, we suggest a model for INPP5E–Leber congenital amaurosis, proposing how deletion of INPP5E may interrupt axoneme extension and disc membrane elaboration." (PMID 33711342, 2021). "INPP5E localizes to the photoreceptor IS and CC, but not to the OS, and retina-specific KO for INPP5E exhibits a rapid rod-cone generation resembling Leber congenital amaurosis (LCA)." (PMID 37780208, 2023).
Hepatic fibrosis (3 papers, 2017 to 2025). The presence of excessive fibrous connective tissue in the liver. "However, many other diseases, including PKD, SHH medulloblastoma, cystic renal dysplasia, hepatic fibrosis, colorectal carcinoma, IRD, monogenic obesity syndrome, and Senior-Loken syndrome, are associated with INPP5E mutations 31, 56-66." (PMID 39781470, 2025).
renal cyst (3 papers, 2018 to 2024). A fluid filled sac in the kidney. "This recessive hypomorphic allele was identified in a forward genetic screen in the mouse that caused rapid cystic renal disease and the analogous mutation in human TULP3, K389I, disrupted ciliary trafficking of ARL13B, GPR161, and INPP5E." (PMID 36276950, 2022).
Ataxia (2 papers, 2019 to 2020). Ataxia refers to impaired coordination of voluntary muscle movement. "However, the phenotype associated with mutations in INPP5E is quite distinct, and includes cerebellar vermis hypo-dysplasia, coloboma, hypotonia, ataxia, and neonatal breathing dysregulation." (PMID 31034465, 2019).
Kidney Cyst (2 papers, 2013 to 2018). Abnormal fluid filled sac within the kidney, either acquired or congenital. "In an Inpp5e knockout mouse model, the mice died soon after birth with an extreme phenotype with multiple anomalies such as anencephaly or exencephaly, bilateral anophthalmos, multiple kidney cysts, postaxial hexadactyly, bifid sternum and delayed ossification of metacarpals and phalanxes." (PMID 30235266, 2018).
microphthalmia (2 papers, 2020 to 2025). Congenital or developmental anomaly in which the eyeballs are abnormally small. "Mutations in INPP5E cause Joubert and Meckel-Gruber syndromes in humans; these are characterized by brain malformations, microphthalmia, situs inversus, skeletal abnormalities, and polydactyly." (PMID 39781470, 2025). "In turn, several mouse mutants defective for TZ proteins are required for Inpp5e localization to cilia and show microphthalmia." (PMID 32840212, 2020).
viral infection (2 papers, 2021 to 2022). "Many of them, such as WDR7, INPP5E, CDK13, VAPA, NAMPT and PUM2, are known to be involved in viral infection mechanisms, whether at the point of the viral entry into the cell or during viral replication." (PMID 35563619, 2022).
cervical cancer (1 paper, 2017). A primary or metastatic malignant neoplasm involving the cervix. "Increased INPP5E transcription was reported in cervical cancers, uterine leiomyomas, and lymphomas (51, –, 53), while decreased INPP5E transcription was found in gastric carcinomas and metastatic adenocarcinomas." (PMID 28031327, 2017).
cone dystrophy (1 paper, 2024). An inherited ocular disorder characterized by the loss of cone cells, the photoreceptors responsible for both central and color vision. "Patient one had a clinical diagnosis of cone dystrophy, and the Invitae kit reported VUS in ARHGEF18, INPP5E, NPHP3, and SEMA4A; BG reported VUS in ARHGEF18 and SEMA4A." (PMID 38892829, 2024).
glioma (1 paper, 2023). A benign or malignant brain and spinal cord tumor that arises from glial cells (astrocytes, oligodendrocytes, ependymal cells). "Indeed, we observed lower INPP5e expression in ARL13bWT:GFP+ glioma cilia." (PMID 37830570, 2023). "Thus, we compared INPP5e expression in parental and ARL13B-overexpressing glioma cells." (PMID 37830570, 2023). "However, glioma cell lines whose cilia overexpress WT but not guanine exchange factor-deficient ARL13B, display reduced INPP5e, a ciliary membrane component whose depletion may favor SMO/GLI2 enrichment." (PMID 37830570, 2023).
Intellectual disability (1 paper, 2021). "Also, other genes encoding proteins of the inositol phosphatase metabolism (e.g., INPP5K, FIG4, INPP5E) are associated with autosomal recessive syndromes of intellectual disability." (PMID 33168985, 2021).
type 2 diabetes (1 paper, 2022). "Intriguingly, both PMPCA and INPP5E showed a significant association with chronotype, which is in opposite directions to type 2 diabetes, indicating that people who are prone to be more an “evening” than a “morning” person have a higher risk for developing type 2 diabetes." (PMID 35203577, 2022). "Our study showed that both PMPCA and INPP5E showed a significant association with chronotype, which is in opposite directions with type 2 diabetes, which suggested that people who are prone to be more of an “evening” than a “morning” person have a higher risk for developing type 2 diabetes." (PMID 35203577, 2022).
tumor (5 papers, 2017 to 2026). "Since Inpp5e deficiency causes profound perinatal lethality in mice, future animal studies should employ inducible or tissue-specific knockout technology to explore the proposed tumor suppressor function of this phosphatase in vivo." (PMID 28031327, 2017).
genetic disorder (2 papers, 2024 to 2025). "INPP5E-related retinopathy refers to a rare genetic disorder caused by pathogenic variants in the INPP5E gene (MIM*613037)." (PMID 41465079, 2025).
neurodevelopmental disorder (2 papers, 2021 to 2022). A behavioral and cognitive disorder with onset during the developmental period that involves impaired or aberrant development of intellectual, motor, or social functions. "The pathomechanism explaining the disease mechanism remains unknown, however several others genes of the inositol phosphatase metabolism (e.g., INPP5K, FIG4, INPP5E, ITPR1) are correlated with phenotypes of neurodevelopmental disorders." (PMID 33168985, 2021).
autosomal recessive disease (1 paper, 2021). Autosomal recessive form of disease. "INPP5E were associated with autosomal recessive diseases, while SEC16A had not been reported to be related to a known disease." (PMID 33898534, 2021).
cancer (1 paper, 2017). A tumor composed of atypical neoplastic, often pleomorphic cells that invade other tissues. "However, the role of INPP5E and other phosphoinositide-5-phosphatases in tumorigenesis is less clear: both up- and downregulation of these enzymes have been reported in cancer." (PMID 28031327, 2017). "These novel roles of INPP5E in cell division may be related to the roles of this phosphatase in development and cancer." (PMID 28031327, 2017). "Our findings demonstrate new mitotic functions of INPP5E, thereby uncovering a new avenue through which INPP5E and phosphoinositides may direct human development and the prevention of cancer." (PMID 28031327, 2017).
INPP5E also shares sentences with these, for which no sentence is quoted: Micropenis (5 papers); Truncal obesity (5); Joubert syndrome 1 (3); Bardet-Biedl syndrome (2); glaucoma (2); nephronophthisis (2); Obesity (2); polydactyly (2); retinal disease (2); retinitis pigmentosa (2); Blindness (1); brain malformations (1); coloboma (1); colon cancer (1); colorectal carcinoma (1); cyst (1); Cystic renal dysplasia (1); Dent disease (1); development (1); gastric carcinoma (1); kidney disease (1); lymphoma (1); Meckel-Gruber syndromes (1); myopia (1); neurological disorders (1); ptosis (1); renal failure (1); retinopathy (1); Septo-optic dysplasia (1); situs inversus (1).
A further 2 diseases each share a sentence with INPP5E in 1 paper.